ATG7 (autophagy related 7)
Diseases named in the same sentence as ATG7 in open-access papers (continued):
Sharing a sentence is not in itself a finding about the gene and the disease.
Infertility (8 papers, 2017 to 2023). "For instance, autophagy‐related gene 7 (Atg7) is a key molecule that is pivotal for fetal mouse ovary development, and Atg7 loss results in infertility in adults." (PMID 32074399, 2020). "For instance, ATG7, on which we focused during the bisulfite-sequencing validation, is involved in autophagy and associated with formation of the acrosome and with spermiogenesis; impairment of these functions in ATG7 −/− germ cell-specific mice drive complete infertility." (PMID 35477426, 2022). "The relative expression of ATG7 wassignificantly higher in infertile men with globozoospermiacompared to fertile subjects (at a ratio of ATG7/GAPDH3.1 ± 0.94 vs. 0.71 ± 0.2; P=0.04)." (PMID 33650822, 2021). "Unlike the relative expression of LC3II/LC3 that did not significantly differ between the twogroups, the relative expression of ATG7 was significantly higher in infertile men with globozoospermia compared tofertile individuals (P<0.05)." (PMID 33650822, 2021). "Assessment of relationship between LC3II/LC3 and Autophagy-related 7 (Atg7) proteins, as markers of autophagy,as well as evaluating the sperm parameters and DNA fragmentation in spermatozoa of infertile men with globozoospermia." (PMID 33650822, 2021). "Autophagy-related protein 7 (Atg7) is essential for mouse acrosome biogenesis during spermatogenesis, depletion of which results in complete infertility with aberrant acrosome formation." (PMID 29340093, 2017). "Subsequently, the expression of ATG7 and the levels of autophagy and apoptosis were found to be increased in males with infertility due to varicocele, which may be related to the elimination of numerous abnormal sperm and the response to heat and oxidative stress." (PMID 35710416, 2022). "Moreover, mouse models lacking an essential autophagy gene, AuTophaGy related 7 (Atg7), are infertile even though specific mechanism remains unclear." (PMID 34709374, 2021).
pancreatitis (8 papers, 2017 to 2025). Inflammation of the pancreas. "Consistently, it has been reported that disruption of autophagy by depletion of ATG5 or ATG7, as well as impairment of lysosomal function, is sufficient to cause spontaneous pancreatitis in mice." (PMID 40577485, 2025). "Twelve-week-old Atg7Δpan mice showed increased activation of trypsin, RIP3, and MLKL at baseline, but more so in response to LPS, suggesting that the depletion of Atg7 from acinar cells is sufficient to predispose the tissue to pancreatitis." (PMID 33087696, 2020). "We have shown that human pancreatitis is associated with disabled autophagic ATG7 and ATG5, as well as a reduction of LAMP2 protein expression, impairing acinar cell autophagy signaling." (PMID 33087696, 2020). "Loss of pancreatic Atg7 has been reported to be sufficient to induce massive acinar cell death associated with pancreatitis." (PMID 28660075, 2017). "The present study reveals that pancreatic Atg7 deletion causes gender-independent severe pancreatitis with progressive cell death, fibrosis and inflammation." (PMID 28703808, 2017). "However, in another study, knocking out Atg5 in the pancreas of mice caused spontaneous pancreatitis, similar to knocking out Atg7." (PMID 38605381, 2024). "In addition, we and others have shown that genetic intervention leading to the local removal of essential autophagy genes such as autophagy-related 5 and 7, Atg5, Atg7, or lysosomal-associated membrane protein-2 (Lamp2) promotes the development of pancreatitis in rodents." (PMID 33087696, 2020). "The microRNA-30b-5p/CAMKII pathway contributes to impaired autophagy promotion in pancreatitis facilitated by Atg7." (PMID 39403146, 2024). "It has also been shown that defective hepatic autophagy promotes ER stress in obese mice and constitutive pancreatitis and ER stress in pancreas specific ATG7 and ATG5 mice." (PMID 37749555, 2023). "Since depletion of pancreatic Atg7 resulted into signs of necrosis and upregulation of Rip3, we investigated whether Rip3 depletion would be able to attenuate pancreatitis." (PMID 28703808, 2017). "Genetic modifications of core autophagy-related proteins like Atg5, Atg7, or LAMP2 in the pancreas lead to severe acinar cell degeneration, exocrine pancreas atrophy, fibrosis, inflammation, and cellular damage, highlighting autophagy impairment’s role in exacerbating pancreatitis severity." (PMID 39403146, 2024).
retinal degeneration (8 papers, 2012 to 2021). Degeneration of the retina. "Deficiency of the autophagy regulatory gene, Atg7, results in light-induced retinal degeneration or RPE degeneration in mice." (PMID 32079136, 2020). "Autophagy deficiency due to depletion of Beclin1 or Atg7 results in light-induced retinal degeneration." (PMID 31209365, 2020). "A recent study indicates that knockdown of Atg7 by GMR-Gal4 on X chromosome causes retinal degeneration." (PMID 22621211, 2012). "Outer hair cell Atg7 deletion resulted in accumulation of dysfunctional mitochondria, causing profound early‐onset hearing loss, and Atg7 deficiency in retinal pigmented epithelia predisposed mice to retinal degeneration." (PMID 34725936, 2021). "During light-exposed photoreceptor degeneration, the deletion of Beclin1 or ATG7 in rod photoreceptor cells induced retinal degeneration via Parkin." (PMID 34066394, 2021). "A recent report showed that mice with a deletion of ATG5 or ATG7 specifically in RPE cells developed inflammation in the eye that resulted in an early onset of retinal degeneration." (PMID 30271775, 2018). "The critical role of autophagy within RPE is emphasized in mice models where the lack of Atg5 or Atg7 focally within RPE cells leads to retinal degeneration compatible with AMD-like phenotypes." (PMID 32756487, 2020). "Such a circadian autophagy rhythm is critical since mice lacking Beclin-1 or Atg7 develop severe retinal degeneration upon light exposure." (PMID 32756487, 2020). "It remains to be determined whether increased ATG7 expression may balance out the lower expression of ATG5 systemically or locally, and whether lower ATG5 expression in AIR patients was a specific contributor to or sign of retinal degeneration." (PMID 30271775, 2018).
acute myeloid leukemia (7 papers, 2015 to 2024). Acute myeloid leukemia (AML) is a group of neoplasms arising from precursor cells committed to the myeloid cell-line differentiation. "For instance, knockdown of Atg7 enhances the sensitivity of acute myeloid leukemia to cytarabine and idarubicin." (PMID 35402237, 2022). "ATG7, an activator of ATG8 involved in the expansion of phagophore, confers chemoresistance in the acute myeloid leukemia cell lines against cytarabine and idarubicin treatment, knockdown of ATG7 increased apoptosis and DNA damage." (PMID 39850800, 2024). "In acute myeloid leukemia (AML), TP53INP2 is upregulated by FTO-mediated modification of m6A, which enhances autophagy activity by promoting the interaction of LC3 and ATG7, ultimately promoting leukemia cell survival." (PMID 38576024, 2024). "WWP1 knockdown in acute myeloid leukemia (AML) cells indeed leads to autophagy induction, which is accompanied by increased total levels of LC3 and ATG7 and accumulation of lipidated LC3." (PMID 31441992, 2019).
adenoma (7 papers, 2012 to 2024). A neoplasm arising from the epithelium. "Consistently, loss of p62 in ATG5 or ATG7-depleted mouse models were found to suppress tumor growth, suggesting there is a correlation between p62 accumulation and adenoma formation." (PMID 39178313, 2024). "Subsequent studies demonstrated that Atg5-/- and Atg7-/- livers give rise to adenomas, Atg4C-/- mice are susceptible to chemical carcinogenesis, and Bif1-/- mice are prone to spontaneous tumors, indicating that autophagy defects promote tumorigenesis." (PMID 23181220, 2012). "During the adenoma-carcinoma sequence, we found Atg7 to be upregulated and Beclin-1 to be downregulated, while LC3b and the scaffold protein p62 stayed unaffected." (PMID 32046105, 2020). "In 2011, two groups independently showed that mosaic deletion of autophagy-related (Atg)-5 in the whole body or liver-specific deletion of Atg7 leads to spontaneous formation of adenoma, a benign tumor, in the mouse liver, confirming the role of autophagy as a suppressor of tumorigenesis." (PMID 35727403, 2022). "For example, Atg5 or Atg7 deletion in mouse liver accelerates adenoma formation." (PMID 35727403, 2022). "In addition, these Atg7-deficient adenomas progressed into oncocytomas as opposed to the adenocarcinomas seen in Atg7-expressing mice." (PMID 35147163, 2022).
renal fibrosis (7 papers, 2019 to 2024). A final common manifestation of a wide variety of chronic kidney diseases characterized by glomerulosclerosis and tubulointerstitial fibrosis. "In our present study, we found that RAGE was induced by TGF-β1 and UUO, and then mediated autophagy to increase the renal fibrosis via STAT3/Atg7 axis in vitro and vivo." (PMID 35461309, 2022). "Second, the inhibition of autophagy impaired the protection of Cana on lipid metabolism disorder and renal fibrosis by Atg7 knockout in tubular cells." (PMID 36685533, 2022). "Mechanistically, RAGE mediated the TGF-β1-triggered Stat3 activation and then promoted autophagy to increase renal fibrosis via upregulation of Atg7." (PMID 35461309, 2022). "Mechanistically, RAGE mediated TGF-β1-induced phosphorylation of Stat3 and directly upregulated the Atg7 to increase the level of autophagy, and ultimately resulting in renal fibrosis." (PMID 35461309, 2022). "In this study, MPs increased the levels of Cd-mediated autophagy marker LC3-II and the autophagy early proteins ATG5, Beclin-1, and ATG7 and increased the levels of the renal fibrosis marker proteins α-SMA, TGF-β1, and COL4A1." (PMID 36430889, 2022). "In order to confirm the role of Atg7 in renal fibrosis, PT-ATG7-KO mice was established, and then subjected to UUO model for 7 days." (PMID 35461309, 2022). "Mechanistically, TGF-β1 stimulated the RAGE and then activated STAT3 to increase autophagy via directly upregulation of Atg7, and then promoted the progression of renal fibrosis." (PMID 35461309, 2022). "Collectively, RAGE in proximal tubular cells promotes the autophagy to increase renal fibrosis via upregulation of Stat3/Atg7 axis." (PMID 35461309, 2022). "The conditional deletion of autophagy related 7 (ATG7) in proximal tubules progressed renal fibrosis induced by unilateral ureteral obstruction." (PMID 30717078, 2019). "The data verified that Atg7 plays an essential role in UUO-induced renal fibrosis." (PMID 35461309, 2022). "To further confirm whether miRNA-122a affects renal fibrosis through the autophagy signaling pathway, we used 3-MA and an ATG7 siRNA to inhibit autophagy in miRNA-122a mimic-transfected and miRNA-NC-transfected HK-2 cells treated with TGF-β1." (PMID 35859725, 2022). "Remarkably, pharmacological inhibition of autophagy with CQ and 3-MA as well as ablation of autophagy-related gene 7 (Atg7) specifically from kidney proximal tubules reduced interstitial fibrosis in UUO, indicating that tubular autophagy in renal tubules promotes renal fibrosis." (PMID 35707397, 2022).
dyslipidemia (6 papers, 2013 to 2025). "This indicates that, under dyslipidemia conditions, Atg7 deficiency has impact on the immunometabolic phenotype of mice on a systemic level which is relevant for further research examining autophagy blockade in models of dyslipidemia in vivo." (PMID 30619297, 2018). "Moreover, autophagy activator rapamycin and inhibitor 3-methyladenine, and small interfering RNA against Atg7 were utilized to verify the role of autophagy in the treatment of metabolic syndrome by KD in oleic acid-induced LO2 cells." (PMID 34122092, 2021). "Moreover, autophagy activator RAP, inhibitor 3-MA and Atg7 siRNA were used to verify the role of AMPK/mTOR-mediated autophagy in the treatment of metabolic syndrome by KD." (PMID 34122092, 2021). "Moreover, hepatic ATG7 mRNA expression was increased in patients with dyslipidemia." (PMID 36674839, 2023). "Therefore, the fact that the hepatic expression of ATG7 is increased in people with dyslipidemia could be because ATG7 is trying to regulate the impact of lipid imbalance in the liver." (PMID 36674839, 2023). "In this sense, we only found higher ATG7 mRNA expression in the presence of dyslipidemia (p = 0.005) but not in the protein analysis." (PMID 36674839, 2023). "We only found higher hepatic expression of ATG7/ATG7 in patients presenting dyslipidemia than in the cohort that did not present it." (PMID 36674839, 2023).
influenza (6 papers, 2014 to 2023). An acute viral infection of the respiratory tract, occurring in isolated cases, in epidemics, or in pandemics; it is caused by serologically different strains of viruses (influenzaviruses) designated A, B, and C, has a 3-day incubation period, and usually lasts for 3 to 10 days. "The increased CD8+ T cell expansion in mice with Atg5 or Atg7 deficiency in dendritic cells and some macrophage populations also correlates with improved control of viral titers and pathology in the influenza infected mice." (PMID 30542350, 2018). "Another study reported that autophagy in CD8+ T cells is dramatically reduced in aged mice, and deficiency in the Atg7 autophagy gene leads to a failure of memory formation in CD8+ T cells against influenza and MCMV infection." (PMID 28895911, 2017). "Deletion of autophagy genes including Epg5, Atg14, FIP200, Atg5 and Atg7 led to influenza resistance." (PMID 36042265, 2022). "Even in the context of a BM chimera, Atg7−/− CD8+ T cells fail to generate a CD8+ Tmem pool following influenza infection, suggesting this defect is cell intrinsic." (PMID 25385531, 2014). "For instance, experimental mice lacking the autophagy gene Atg7 in T cells failed to establish memory CD8+ T cells specific for influenza and MCMV infection." (PMID 36625233, 2023). "Mice lacking the autophagy gene Atg7 in T cells exhibit defective memory CD8+ T cell formation in response to influenza and murine cytomegalovirus infection." (PMID 28895911, 2017). "While Atg7−/− T cells respond normally during the early stages of live viral challenge, a severely compromised memory CD8+ T cell compartment was found in response to influenza and murine cytomegalovirus (MCMV)." (PMID 25385531, 2014). "Mice lacking the autophagy gene Atg7 in T cells failed to establish CD8+ T cell memory to influenza and MCMV infection." (PMID 25385531, 2014). "However, treatment with spermidine induced autophagy in T cells and increased influenza-specific CD8+ T cell responses in old vaccinated wild-type mice, but not in the old vaccinated T cell-Atg7 knockout mice." (PMID 28895911, 2017). "Using a mouse model where the essential autophagy gene Atg7 is deleted in T cells under the CD4-promoter (T-Atg7-/- mice), we showed that the CD8+ T cell effector phase proceeds in a normal fashion in the absence of autophagy to influenza and murine cytomegalovirus (MCMV) infection." (PMID 28357282, 2015).
ischemia (6 papers, 2016 to 2025). A hypoperfusion of the BLOOD through an organ or tissue caused by a PATHOLOGIC CONSTRICTION or obstruction of its BLOOD VESSELS, or an absence of BLOOD CIRCULATION. "In the current study, endothelium-specific Atg7 knockout (Atg7 eKO) mice were used to assess the role of endothelial Atg7 in brain injury caused by ischemia/reperfusion." (PMID 30555402, 2018). "Experiments conducted with Atg7 C402S–knockin mice showed that S-nitrosylation of Atg7 at Cys402 promotes autophagy by stimulating E1-like activity, thereby protecting the heart against ischemia." (PMID 36480290, 2023). "Taken together, our results suggest that Trx1 promotes autophagy through transnitrosylation of Atg7, thereby protecting the heart against ischemia." (PMID 36480290, 2023). "In the current study, we utilized endothelial-specific Atg7 knockout mice to investigate the role of endothelial Atg7 in the brain lesions occurring in response to ischemia/reperfusion." (PMID 30555402, 2018). "In fact, although Atg7 deficiency in neurons was reported to provide neuroprotection from brain injury in mice, Atg7 silencing aggravated ischemia-induced brain damage." (PMID 30555402, 2018). "In the current study, we investigated the effect of brain endothelial Atg7 (autophagy related 7) depletion in the acute brain injury induced by ischemia and reperfusion." (PMID 30555402, 2018). "The hypothesis was that if increased p-S6 in the tubules was driving TLT formation and growth, the Atg7−/−Raptor−/− mice exposed to ischemia would have fewer TLTs than control Atg7−/− mice exposed to ischemia." (PMID 40496859, 2025). "Next, we investigated whether Atg7 is S-nitrosylated in response to stress such as ischemia in the heart." (PMID 36480290, 2023). "We speculate that Atg7-mediated activation of autophagy protects the heart against ischemia through preservation of ATP and the cellular quality-control mechanisms." (PMID 36480290, 2023). "In cerebral-I/R, 3MA and Atg7 knockdown to inhibit autophagy reinforced the brain and cell injury in the reperfusion phase, whereas the mitophagy inhibitor Mdivi-1 in the reperfusion phase and Park2 knockdown aggravated the ischemia-induced neuronal injury." (PMID 27148058, 2016). "It should be noted that Trx1 mediates S-nitrosylation of Atg7 even under basal conditions, without GD or ischemia, in the heart in vivo." (PMID 36480290, 2023). "Based on these studies, one may assume that there is no perfect model of ischemia that fully reflects all the features of autophagy, including ATG7, LC3 and autophagosome formation." (PMID 30778709, 2019).
lymphopenia (6 papers, 2012 to 2022). Reduction in the number of lymphocytes. "T cell-specific deficiency of Atg7 compromises single positive T cell generation in the thymus and induces peripheral lymphopenia." (PMID 30619297, 2018). "To exclude that a failure to maintain a CD8+ Tmem pool is caused by lymphopenia in T-Atg7−/− mice, we performed viral challenge experiments in 1:1 mixed BM chimeras, facilitating the observation of antigen-specific Atg7−/− CD8+ T cell responses in a replete T cell environment." (PMID 25385531, 2014). "The lymphopenia upon specific deletion of Atg3, Atg5, Atg7, Atg16l1, or Vps34 in T cells has been demonstrated to be associated with increased percentages of activation/memory-like T cells within both the CD4+ and CD8+ compartments." (PMID 28572806, 2017). "This indicates that without lymphopenia, exhaustion is not a hallmark of Atg7−/− CD8+ T cell responses and cannot explain the diminished CD8+ Tmem compartment." (PMID 25385531, 2014). "In vivo transferred T-cells up-regulate expression of Bcl-2, FoxO1, Eomes and Atg7, enhance the phosphorylation of pSTAT5 and ULK1 and activate the mitochondrial biogenesis via IL-15 signaling in lymphopenia." (PMID 27158441, 2016). "Enhanced T cell activation/memory in the absence of Atg3, Atg5, Atg7, Atg16l1, or Vps34 can be partially attributed to peripheral T cell lymphopenia." (PMID 28572806, 2017). "In this study, investigating a mouse model lacking the essential autophagy gene Atg7 specifically in T cells, we find peripheral T cell lymphopenia, leading to proliferation and an activated phenotype within the CD8+ T cell compartment." (PMID 25385531, 2014). "Similarly, data from a mouse model in which another essential autophagy gene, Atg5, was deleted under the hematopoietic stem cell-specific promoter Vav, showed T cell lymphopenia and the expanded virtual memory T cell compartment (CD8+CD44+) suggesting this phenotype is not Atg7 specific." (PMID 25385531, 2014).